TSPAN8 (tetraspanin 8)
Diseases named in the same sentence as TSPAN8 in open-access papers (continued):
Sharing a sentence is not in itself a finding about the gene and the disease.
breast carcinoma (continued). "Here, in breast cancer the authors highlight a role for TSPAN8 in promoting tumorigenesis through the activation of Hedgehog signalling." (PMID 31253779, 2019). "Similar inhibitory effect of TSPAN8 depletion on growth of mouse tumors derived from primary cancer cells of breast cancer patients was also observed." (PMID 31253779, 2019). "We also tested mRNA isolated from cancer patient samples and detected different levels of TSPAN8‐coding mRNA in 4/7 primary tumours and 6/7 lymph node metastases, further supporting a role for TSPAN8 in breast cancer." (PMID 30982971, 2019). "To examine the role of TSPAN8 in tumorigenesis, we injected 1 × 103–1 × 106 of TS+ or TS− primary breast cancer cells isolated from three patients’ breast cancer specimens into the breast fat pad of NOD/SCID mice to conduct a limiting dilution type assay." (PMID 31253779, 2019). "To assess the direct impact of Tspan8 on breast cancer growth and progression, we chose a syngeneic rat breast cancer model." (PMID 30982971, 2019). "Overexpressed in breast cancer cells, Tspan8 induced E‐cadherin expression and mediated a strong down‐regulation of Twist and β‐catenin target genes." (PMID 30982971, 2019). "We next examined TSPAN8 expression levels in patients with different molecular pathological breast cancer subtypes, including luminal A, luminal B, HER2, and triple-negative breast cancer (TNBC)." (PMID 31253779, 2019). "The establishment of the critical role of TSPAN8 in promoting cancer cell stemness, breast cancer development, and resistance to chemotherapy, makes TSPAN8 a molecular target for therapy of human malignancies." (PMID 31253779, 2019). "To sum up, we have described here the first study on TSPAN8 in breast cancer and have demonstrated the impact of Tspan8 on adhesion, proliferation, radiation resistance, and EV release." (PMID 30982971, 2019). "In a syngeneic rat breast cancer model, Tspan8+ tumours formed multiple liver and spleen metastases, while Tspan8− tumours exhibited a significantly diminished ability to metastasise, indicating a role of Tspan8 in metastases." (PMID 30982971, 2019). "Exploring whether pathways regulated by Mycn in mammary development are abnormally activated in breast cancer, as well as the expression correlation of Mycn, Bcl11b, and Tspan8 in human breast cancer samples, will be of significant value." (PMID 40862719, 2025). "However, TSPAN8 (human) has been shown to enhance breast cancer cell stemness through sonic hedgehog signaling activation, introducing additional complexity to understanding Mycn’s contribution to tumor progression." (PMID 40862719, 2025). "Moreover, the role of tetraspanin 8 in breast cancer progression has been demonstrated in in vivo experiments, using MCF‐7 and MDA‐MB‐231 breast cell line xenografts." (PMID 39031113, 2024). "This is the first research to investigate Tspan8 expression and function in breast cancer." (PMID 36059497, 2022). "In breast cancer and liver hepatocellular carcinoma, high expressions of TSPAN8 were observed." (PMID 34163029, 2021). "The expression level of TSPAN8 is upregulated in breast cancer stem cells." (PMID 32138170, 2020). "Importantly, TSPAN8 expression levels were reversely correlated with the overall survival time of breast cancer patients." (PMID 31253779, 2019). "Here, we addressed the molecular mechanisms of TSPAN8 action in breast cancer cells." (PMID 30982971, 2019). "We present a first study on the expression and function of Tspan8 in breast cancer." (PMID 30982971, 2019). "Recently, Tspan8 was identified as a biomarker for a subset of deeply quiescent mammary stem cells (Lgr5+Tspan8hi), whose transcriptome resembled claudin‐low breast carcinoma 18, thus indicating a potential role in breast cancer." (PMID 30982971, 2019). "Interaction with E‐cadherin resulted in a functional switch of Tspan8 in breast cancer." (PMID 30982971, 2019).
breast carcinoma (continued). "Similarly, depletion of TSPAN8 or ATXN3 in primary cancer cells derived from breast cancer patients decreased these cells sphere formation efficiency and enhanced their sensitivity to chemotherapeutic agents." (PMID 31253779, 2019). "Next, we tested the effect of Tspan8 on the tumourigenic properties of breast cancer cells in vivo." (PMID 30982971, 2019). "To further investigate the clinical significance of TSPAN8 expression, we performed immunohistochemical staining (IHC) analyses of an additional cohort of human breast cancer specimens, determined the correlation between TSPAN8 expression and the response rate to chemotherapy." (PMID 31253779, 2019). "However, the MTPa‐Tspan8 tumours formed multiple metastases in the liver and spleen, suggesting a role for Tspan8 in metastases in breast cancer." (PMID 30982971, 2019). "Importantly, TSPAN8 and ATXN3 expression levels were associated with poor prognosis in breast cancer patients." (PMID 31253779, 2019). "In addition, FACS and immunoblotting analyses showed that PTX and ADR increased the ratio of TSPAN8 and enhanced TSPAN8 protein expression in both TS+ and TS− primary breast cancer cells." (PMID 31253779, 2019). "In this work, we propose a new function of Tspan8 as an EMT–MET regulator in breast cancer." (PMID 30982971, 2019). "In addition, a positive association between the expression levels of TSPAN8 and SHH, as well as between PTCH1 and ATXN3, in breast cancer specimens was observed." (PMID 31253779, 2019). "At the molecular level, Tspan8 promotes invasion by ProMMP9 activation or β-catenin loop stimulation in melanoma, regulates E-cadherin/catenin signalling and metastasis in colorectal and breast cancer, and induces cancer stemness through sonic hedgehog signalling in breast cancer." (PMID 37835445, 2023). "Validated down-regulated genes include NPC2 involved in the negative regulation of MAPK, TSPAN8 involved in tumor progression and metastasis, ANKRD1 mainly expressed in MDA-MB231 breast cancer cell lines and linked to treatment-resistance in breast cancer, and FST involved in metastasis suppression." (PMID 34680207, 2021). "Addressing the question of the selective advantages mediated by TSPAN8 in breast cancer, we observed that Tspan8+ cells exhibit significantly greater radiation resistance compared with control Tspan8− mesenchymal‐like cells, suggesting that MET may also be linked to radiation resistance." (PMID 30982971, 2019). "TSPAN8 (+) myCAFs can resist chemotherapy by secreting SASP related factors IL-6 and IL-8, thus enhancing the stemness of surrounding breast cancer cells." (PMID 40626005, 2025). "Nuclear localization of tetraspanin 8 was observed in several cell lines, including SW1990 (pancreatic cancer), MDA‐MB‐231 (breast cancer), SW620 (colon cancer), HGC‐27 and AGS (stomach cancer), and also U‐87 MG and U251 MG (glioblastoma cell lines)." (PMID 39031113, 2024). "To extend these findings, we investigated TSPAN8 and THRSP expression among the germline BRCA2-mutant tumours in the TCGA breast cancer dataset." (PMID 37626143, 2023). "These experiments strongly suggest that TSPAN8 together with ATXN3 promote the Hedgehog signaling and breast cancer progression by enhancing PTCH1 and SHH expression." (PMID 31253779, 2019). "Meanwhile, TSPAN8 could induce the EMT process and enhance cell–cell adhesion of breast cancer cells via interacting with p120." (PMID 36941633, 2023). "Several new membrane proteins and prognostic markers have been reported to regulate stemness in specific subtypes of breast cancer, such as protein C receptor (PROCR), tetraspanin 8 (TSPAN8), tumor endothelial marker 8 (TEM8), epsilon sarcoglycan (SGCE), and Ki-67." (PMID 36230903, 2022).
breast carcinoma (continued). "To address the possibility of TSPAN8 playing a role in breast cancer, we first tested seven breast cancer cell lines 22 for TSPAN8 expression and observed that only MDA‐MB‐361 cells derived from brain metastases exhibited high levels of TSPAN8." (PMID 30982971, 2019). "In this study, we analysed the expression of Tspan8 in breast cancer in primary lesions and in metastases in humans and examined its impact on the EMT–MET programme in breast cancer cells and on the release and function of extracellular vesicles using a syngeneic rat breast cancer model." (PMID 30982971, 2019). "To determine the clinical relevance of TSPAN8- and ATXN3-regulated PTCH1/SHH stability, we performed IHC staining of 90 breast cancer specimens and found that the expression of TSPAN8 in the tumor tissue was higher than that in the adjacent non-tumor tissue." (PMID 31253779, 2019). "To further determine whether TSPAN8 is a CSCs marker, we used flow cytometry to separate TSPAN8-highly expressed (TS+) from TSPAN8-lowly expressed (TS−) cells in non-cultured primary breast cancer cells derived from three independent patients." (PMID 31253779, 2019). "Analyses of the expression levels of all 33 tetraspanins revealed significantly higher expression of TSPAN1, TSPAN15, TSPAN8, TSPAN11, TSPAN29, and TSPAN27 in the breast cancer spheres than in non-CSCs." (PMID 31253779, 2019).
pancreatic cancer (23 papers, 2007 to 2025). "SOX9 positively regulates endogenous Tspan8 expression at the transcriptional level and also leads to loss of cell matrix adhesion and increased invasion in pancreatic cancer cells." (PMID 38389703, 2024). "Tspan8 has been identified as a biomarker for pancreatic cancer, and its co-localization with CD151-α6β4 has been associated with decreased adhesion and enhanced motility of pancreatic cancer cells." (PMID 38389703, 2024). "The gene product of TSPAN8 has been implicated in regulating metastasis in pancreatic cancer and is a proposed target candidate for immunotherapy for pancreatic cancer." (PMID 36812168, 2023). "For instance, tetraspanin 8 (Tspan8) selectively associates with integrin α4β1 in pancreatic cancer exosomes." (PMID 33672100, 2021). "Over-expression of TSPAN8 has been reported in many digestive system neoplasms including colorectal, liver, esophageal, and pancreatic cancer, and is associated with poor prognosis." (PMID 27270327, 2016). "For instance, TSPAN8 is one of the markers used to characterize pancreatic cancer stem cells (Pa-CSCs)." (PMID 38275818, 2024). "One recent study reported that Tspan8 can be used as a specific target candidate for chimeric antigen receptor T cells (CAR-T) against pancreatic cancer." (PMID 38389703, 2024). "TSPAN8 and CD44v6 mark pancreatic cancer stem cells (CSCs) and play a critical role in exosome biogenesis, loading, and delivery." (PMID 38275818, 2024). "Another study reported that in pancreatic cancer cells with high TSPAN8 expression, tumor-derived EVs enhanced the maturation and activation of endothelial and fibroblast cells in the tumors." (PMID 38275818, 2024). "TSPAN8 also facilitates metastasis of pancreatic cancer cells in vivo and in vitro, while it promotes metastasis of rat pancreatic cancer cells through recruiting integrins out of adhesion into motility promoting complexes." (PMID 36941633, 2023). "We identified TSPAN8 as a potential tumor-specific gene significantly overexpressed in pancreatic tumor tissue in Black patients as compared to White patients." (PMID 36812168, 2023). "Research has demonstrated that the CD44v6 and tetraspanin 8 (Tspan8) axis is involved in EV formation in pancreatic cancer." (PMID 35501802, 2022). "The results suggested that the expression level of TSPAN8 was significantly elevated in the malignant pancreatic cancer cell lines BxPC-3, AsPC-1 and SW1990 compared with the normal cell line HPDE6-C7." (PMID 34163029, 2021). "As a result, the expression of rescue TSPAN8 significantly reversed the inhibitory effect of TSPAN8 depletion on cellular invasion, suggesting that TSPAN8 has an important role in enhancing pancreatic cancer cell invasion." (PMID 34163029, 2021). "After CD44v6-knockdown pancreatic cancer cells were transplanted into mice, anti-Tspan8 antibodies was able to block the transmission of Tspan8+ sEVs information in mice, thus inhibiting the growth and spread of these tumor cells." (PMID 34094979, 2021). "Tetraspanin 8 (TSPAN8), a membrane glycoprotein, is known to be highly expressed in pancreatic cancer and contributes to the increase in migration and angiogenesis." (PMID 32756339, 2020). "In pancreatic cancer, both TSPAN8 and α6β4 integrin are highly expressed and correlate with increased tumor cell motility by promoting integrin activation through focal adhesion kinase, paxillin and Src recruitment." (PMID 32138170, 2020). "Interestingly, a study by Biel and colleagues examined gene expression profiles of pancreatic tumors from 5 BAA and 11 White patients and identified elevated levels of TSPAN8, a gene known to play crucial roles in pancreatic cancer, in BAA patients." (PMID 39699266, 2025). "Furthermore, SOX9 was identified as a key transcriptional regulator of TSPAN8 expression in response to EGF stimulation in pancreatic cancer cells." (PMID 38275818, 2024).
pancreatic cancer (continued). "Interestingly, Daniel and colleagues identified that TSPAN8 can be used as a specific target candidate for chimeric antigen receptor T cells (CAR-T) against pancreatic cancer among 371 antigens." (PMID 36941633, 2023). "In addition, the membrane proteins CD44v6 and Tspan8 from the sEVs of pancreatic cancer initiation cells can render non-tumor initiation cells the ability to promote the occurrence and development of pancreatic cancer." (PMID 34094979, 2021). "Moreover, increased SOX9 and TSPAN8 levels were shown to correlate in human pancreatic cancer specimens and downregulated in vitro by EGFR tyrosine kinase inhibitors." (PMID 34163029, 2021). "Pancreatic cancer-initiating cells (PaCIC) express CD44v6 and Tspan8." (PMID 31485223, 2019). "Through our ELISA assay we measured levels of different exosome populations, in particular those carrying the ubiquitous CD9, CD81 and some markers already found in tumour exosomes of pancreatic cancer such as CD44v6, Tspan8, EpCAM, CD24, CXCR4, Integrins α6 and β4, CD133." (PMID 31048929, 2019). "Recent studies have shown that monoclonal antibodies targeting tetraspanin 8 can be used in ovarian cancer, and moreover in CAR‐T therapy for pancreatic cancer." (PMID 39031113, 2024). "In another study, TSPAN8, alongside CD44v6, an α6β4 integrin, and CD133, were found to be upregulated in pancreatic cancer-initiating cells (Pa-CIC), where they conferred in vivo growth and metastatic advantages." (PMID 38275818, 2024). "To identify the correlation between the expression levels of TSPAN8, SOX9 and EGFR in PDAC, we performed IHC analysis of an additional cohort of 40 human pancreatic cancer specimens." (PMID 34163029, 2021). "To determine the biological roles of TSPAN8 in PDAC metastasis, we carried out an immunoblotting analysis of TSPAN8 expression in a panel of pancreatic cancer cell lines with different metastatic potential." (PMID 34163029, 2021). "We used anti-Tspan8 to block pancreatic cancer TEX, Tspan8 being abundantly expressed on pancreatic CSC-TEX." (PMID 29456536, 2018). "Collectively, these preliminary data suggest that GSTM1 and TSPAN8 are upregulated in pancreatic tumors in Black patients we tested in comparison to non-tumorous pancreatic tissue in Black patients and either pancreatic tissue in White patients." (PMID 36812168, 2023).
melanoma (20 papers, 2011 to 2025). A malignant, usually aggressive tumor composed of atypical, neoplastic melanocytes. "Recently conducted studies have shown that tetraspanin 8 expression in melanomas can be associated with the invasive form of cutaneous melanoma." (PMID 39031113, 2024). "TSPAN8 was shown to function as a negative regulator of integrin-linked kinase driven β1 integrin-dependent adhesion in melanoma cells, thereby decreasing adhesive interaction with the surrounding matrix environment and promoting tumor invasiveness." (PMID 36922633, 2024). "Experimental data suggest that this loss results in increased tetraspanin 8 expression and a tetraspanin 8‐dependent increase in melanoma cell invasion." (PMID 39031113, 2024). "Lung cancer metastasis-related protein 1 (LCMR1) enhances the TSPAN8 expression and promotes the loss of melanoma cell-matrix adherence (mainly through β1-integrin-ILK axis) and increases in invasion in vitro and tumorigenicity in vivo." (PMID 32138170, 2020). "We previously reported that Tspan8 is a hallmark of melanoma progression, responsible for the acquisition of an invasive phenotype." (PMID 28188308, 2017). "Several TSPAN8 transcriptional regulators were identified, including lung-cancer metastasis-related protein 1, which increases TSPAN8 expression and causes loss of melanoma cell–matrix adherence, leading to cell invasion." (PMID 28368391, 2017). "Interestingly, we found that the switch in EMT-TF expression that we described in human melanomas was also clearly observed during melanoma progression in medaka fish and was associated with an increase in Tspan8 expression." (PMID 38398085, 2024). "We collected samples from mitf::Xmrk/+ medaka and compared SNAI2, ZEB1, and Tspan8 expression in normal skin, primary melanomas, and melanoma local metastases." (PMID 38398085, 2024). "TSPAN8 is prominently expressed in melanoma, a particularly aggressive form of skin cancer with a high metastatic potential, where it is involved in regulating the invasive properties of these malignant cells." (PMID 38275818, 2024). "We found that silencing the SNAI2 and ZEB2 transcription factors, which behave as tumor suppressors in melanoma cells, significantly induced Tspan8’s endogenous expression at both the mRNA and protein levels in different melanoma cell lines." (PMID 38398085, 2024). "The morphological and mechanical adaptation of melanoma cells induced by the EMT-TF expression switch seems to be mainly mediated by Tspan8 expression regulation." (PMID 38398085, 2024). "In melanoma fish samples, we detected the appearance of Tspan8 expression both at the mRNA and at the protein level, detected by Western blot and immunohistochemistry." (PMID 38398085, 2024). "We demonstrated that ZEB1 overexpression in melanoma cells was indeed able to activate Tspan8 mRNA and protein expression." (PMID 38398085, 2024). "As expected, the morphological parameters of melanoma cells in which Tspan8 expression was modulated were also consequently modified." (PMID 38398085, 2024). "A monoclonal TSPAN8 antibody was able to block the activation of proMMP-9 and subsequent dermal invasions by melanoma cells." (PMID 38275818, 2024). "In vitro experiments showed that tetraspanin 8‐overexpressing melanoma cells activated pro‐MMP‐9, leading to the degradation of type IV collagen and colonization of the dermis." (PMID 39031113, 2024).